HSPB6 (heat shock protein family B (small) member 6)
Description:
Small heat shock protein which functions as a molecular chaperone probably maintaining denatured proteins in a folding-competent state. Seems to have versatile functions in various biological processes. Plays a role in regulating muscle function such as smooth muscle vasorelaxation and cardiac myocyte contractility. May regulate myocardial angiogenesis implicating KDR. Overexpression mediates cardioprotection and angiogenesis after induced damage. Stabilizes monomeric YWHAZ thereby supporting YWHAZ chaperone-like activity.
Synonyms: FLJ32389; Hsp20; PPP1R91; HEL55
Tractability: Antibody: UniProt places it where antibodies can reach, with high confidence; its Gene Ontology location is reachable by antibodies, with high confidence.
Gene: Protein-coding gene on chromosome 19 (35,754,566 to 35,758,079, reverse strand). Ensembl gene ENSG00000004776.
Subcellular location: Cytoplasm; Nucleus; Secreted
Subcellular location (Human Protein Atlas): Cytosol; Mitochondria; Nuclear speckles
Gene Ontology:
Molecular function: 14-3-3 protein binding; protein folding chaperone; protein-folding chaperone binding; protein homodimerization activity; protein kinase binding; structural constituent of eye lens
Biological process: positive regulation of angiogenesis; protein folding; negative regulation of apoptotic process; protein refolding; response to heat; negative regulation of cardiac muscle cell apoptotic process
Cellular component: cytoplasm; cytosol; extracellular region; nuclear speck; nucleus
Genetic constraint (gnomAD): Loss-of-function variants: 13 observed, 8.33 expected, observed/expected ratio (o/e) 1.56, 90% interval 0.98 to 1.94. That is too few expected variants to judge how well the gene tolerates losing a copy. Missense variants: 232 observed, 179.4 expected, observed/expected ratio (o/e) 1.29, 90% interval 1.16 to 1.44. Synonymous variants: 128 observed, 93.13 expected, observed/expected ratio (o/e) 1.37, 90% interval 1.19 to 1.59.
Homologues: Orthologues: chimpanzee HSPB6 (100% identical), macaque HSPB6 (99% identical), pig HSPB6 (94% identical), dog HSPB6 (92% identical), guinea pig HSPB6 (92% identical), rat Hspb6 (90% identical), mouse Hspb6 (89% identical), rabbit HSPB6 (76% identical), tropical clawed frog hspb6 (56% identical), zebrafish hspb6 (36% identical), Drosophila melanogaster Hsp27 (34% identical), Caenorhabditis elegans hsp-12.2 (27% identical), and 7 more. Paralogues in human: CRYAB (49% identical), CRYAA (41% identical), HSPB2 (38% identical), HSPB1 (37% identical), HSPB8 (27% identical), HSPB7 (26% identical), HSPB3 (23% identical), HSPB9 (19% identical).
Diseases named in the same sentence as HSPB6 in open-access papers:
HSPB6 is named in the same sentence as 87 diseases in open-access papers, as found by Europe PMC text mining. Sharing a sentence is not in itself a finding about the gene and the disease. The quoted sentences say what the papers report.
diabetes (9 papers, 2017 to 2024). "The miR-320-3p has been studied for post-transcriptional gene silencing in the cytoplasm on rat endothelial and cardiac cell cultures derived from diabetes situation [on several genes among which the heat shock protein family B (small) member 6 (Hspb6) or Hsp20]." (PMID 31456698, 2019).
hepatocellular carcinoma (9 papers, 2013 to 2024). A malignant tumor that arises from hepatocytes. "A strong finding has also indicated that HSPB1 and HSPB6 formation results in a reduction in the progression of hepatocellular carcinoma." (PMID 37241227, 2023). "HSPB6 can inhibit the growth of hepatocellular carcinoma by inhibiting the AKT pathway, and in other cancers, it is also found to inhibit the growth of cancer and can be used as a new marker for cancer diagnosis." (PMID 29301256, 2018). "Interestingly, similar data have shown that HSPB6 expression is downregulated in ovarian cancer, hepatocellular carcinoma, and CC." (PMID 37241227, 2023). "The investigation into HSPB6's involvement in cancer has been expanding, with a 2007 study identifying its presence in hepatocellular carcinoma (HCC) tissues, followed by further research into its role in HCC." (PMID 39608715, 2024). "HSPB6, also termed HSP20, serves as a remarkable member of heat shock protein family and showed scarce expression in human hepatocellular carcinoma (HCC) cell lines." (PMID 37861934, 2023). "Additionally, a report on tumor and non-tumor tissues extracted from patients with hepatocellular carcinoma showed that the expression of HSPB6 was elevated in the non-tumor tissues compared to the tumor tissues, and it has a direct link with BAX to regulate apoptosis." (PMID 37241227, 2023).
heart failure (7 papers, 2013 to 2024). Inability of the heart to pump blood at an adequate rate to meet tissue metabolic requirements. "Similar to other heat shock proteins, HSPB6 exhibits chaperone-like activity and has been shown to prevent heart failure." (PMID 38374143, 2024). "Recent work examining tissue from the RV of human heart failure patients found a set of genes that are unique to RV failure compared to LV failure: WIPI1, HSPB6, SNAP47 and MAP4." (PMID 31960631, 2020).
breast carcinoma (6 papers, 2013 to 2024). "These include FAM183A, which is upregulated in breast cancer cells in response to Notch signaling; MUC4, expressed in 95% of breast carcinomas; HSPB6, which is downregulated in breast cancer; and CCL28, which promotes breast cancer proliferation, tumor growth and metastasis." (PMID 33957961, 2021). "Our study revealed a consistent decrease in HSPB6 expression across various cancers, including BLCA, breast carcinoma, and cervical squamous cell carcinoma, among others." (PMID 39608715, 2024). "Another interesting observation from the present study is that several HSPs were downregulated in all breast cancer subtypes: DNAJB4, DNAJC18, HSPA12A, HSPA12B, HSPB2, HSPB6, and HSPB7." (PMID 29954368, 2018).
cardiomyopathy (5 papers, 2018 to 2026). A disease of the heart muscle or myocardium proper. "Noteworthy, mutations in BAG3, the obligatory partner of HSPB8, cause cardiomyopathy, besides neuropathy and myopathy, and mutations in other HSPBs (HSPB5, HSPB6, and HSPB7) also associate with cardiac pathology." (PMID 40467930, 2025). "While HSPB6 variants have been implicated in cardiomyopathy, they have not been previously linked to neuromuscular disease." (PMID 41294008, 2026). "One study reported that reduced the proteasomal degradation of Beclin-1 by HSPB6 exerted a cardioprotective effect, whereas another study found that the Beclin1 knockdown in cardiomyocytes exposed to high glucose in a model of type 2 diabetes-induced cardiomyopathy decreased apoptotic cell death." (PMID 40894905, 2025).
melanoma (5 papers, 2017 to 2025). A malignant, usually aggressive tumor composed of atypical, neoplastic melanocytes. "Genome-wide screening of promoter methylation has identified that the frequency of HSPB6 promoter methylation increases moderately in early stage melanomas and significantly in advanced-stage melanomas." (PMID 32441304, 2020). "Promoters of COL1A2, HSPB6, NPM2, MT1G or DDIT4L were identified as hypermethylated in melanoma cells suggesting that they can be used as predictors for melanoma progression." (PMID 40427015, 2025). "The results were validated by bisulfite sequencing of COL1A2, NPM2, HSPB6, DDIT4L, and MT1G promoters, which exhibited increasing incidence with advanced melanoma stage, suggesting potential use as predictors of melanoma progression." (PMID 28396701, 2017). "Interestingly, an increase in HSP27 expression was observed after exposure to a higher temperature in all melanoma cells: HSPB1 (A375 and G-361), and HSPB6 (SK-MEL-1) and HSP40: DNAJC4 (A375, G-361, and SK-MEL-1)." (PMID 37886980, 2023).
ovarian carcinoma (4 papers, 2018 to 2023). A malignant neoplasm originating from the surface ovarian epithelium. "HSPB6 expression has been found to be depleted in ovarian cancer and colorectal cancer, and its presence drives HCT116 cells to undergo apoptosis events by inducing caspase 3/7 expression and inhibiting BCL2 expression." (PMID 37241227, 2023). "To identify the involvement of small HSPs (HSPB5, HSPB6, and HSPB8) in OvCa during the development of chemoresistance, we used OvCa cell lines: A2780 and SKOV3, which represents distinct types of ovarian cancer cell lines." (PMID 34177409, 2021).
colorectal cancer (3 papers, 2018 to 2023). A primary or metastatic malignant neoplasm that affects the colon or rectum. "Interestingly, HSPB6 and ITGA7 were downregulated in colorectal cancer, suggesting potential transcriptional positive regulation." (PMID 37241227, 2023).
Insulin resistance (3 papers, 2013 to 2022). Increased resistance towards insulin, that is, diminished effectiveness of insulin in reducing blood glucose levels. "IGF2 plays a key role in glucose metabolism, HSPB6 is associated with insulin resistance, and MCF2L2 is related to type 1 diabetes and polycystic ovary syndrome." (PMID 34645493, 2021). "IGF2 plays a key role in glucose metabolism, HSPB6 might be associated with insulin resistance, and MCF2L2 might be one of the most important marker genes contributing to type 1 diabetes and polycystic ovary syndrome." (PMID 34645493, 2021).
lymph node metastasis (3 papers, 2018 to 2024). "The clinical information analysis indicated that HSPB6 expression was negatively correlated with Gleason score, T classification, lymph node metastasis, and distant metastasis, highlighting its significance as a clinical indicator." (PMID 38374143, 2024).
distal myopathies (2 papers, 2024 to 2025). "Variants in SMPX, DNAJB2, and HSPB6 have been identified as a novel cause of late-onset distal myopathy and neuromyopathy." (PMID 39017652, 2024).
lung carcinoma (2 papers, 2018 to 2021). "We also performed in vitro experiments to explore the functional role of other methylation drivers (IRX1, TBX5 and HSPB6) in lung cancer cell lines." (PMID 33859751, 2021). "In our study, HSPB6 was significantly hypermethylated and downregulated in most of the tumor tissues, suggesting that it plays a protective role in the onset of lung cancer in Xuanwei." (PMID 30286088, 2018). "In addition, we validated the tumor-suppressive role of IRX1, TBX5 and HSPB6 in lung cancer." (PMID 33859751, 2021). "The remaining eight genes are newly identified methylation drivers in lung cancer, including 5 known cancer methylation driver genes in other cancer types (HSPB6, IRX1, ITGA5, PCDH17, TBX5) and 3 novel genes that had not been previously reported (ADCY8, GALNT13 and TCTEX1D1)." (PMID 33859751, 2021). "Moreover, all of the eight novel hypermethylation driver genes (PCDH17, IRX1, ITGA5, HSPB6, TBX5, ADCY8, GALNT13 and TCTEX1D1) were successfully validated in an independent cohort via a pyrosequencing approach, with an AUC of 0.965 for prediction of lung cancer patients." (PMID 33859751, 2021).
Obesity (2 papers, 2024 to 2025). Accumulation of substantial excess body fat. "The upregulation of Hspb6 in our diet-induced obesity model explains why a high-fat diet alone is insufficient to induce AF." (PMID 40565066, 2025).
prostate carcinoma (2 papers, 2022 to 2024). A carcinoma that arises from epithelial cells of the prostate gland. "Herein, we investigated the expression of HSPB6 in prostate cancer and its association with prognosis." (PMID 38374143, 2024). "It is well-established that HSPB6 can induce apoptosis in prostate cancer cells, but the underlying mechanism remains unclear." (PMID 38374143, 2024). "Our results revealed that the combined treatment was more effective than either treatment alone in inhibiting the growth of prostate cancer through the HSPB6 pathway, both in vitro and in vivo." (PMID 38374143, 2024). "Our study found that HSPB6 expression is downregulated in prostate cancer, and this downregulation inhibits tumor progression by inducing apoptosis." (PMID 38374143, 2024). "This further demonstrates that cGMP activates HSPB6 and promotes apoptosis in prostate cancer cells." (PMID 38374143, 2024). "Overall, our study provides compelling evidence that HSPB6 suppresses malignant behavior in prostate cancer by inducing apoptosis." (PMID 38374143, 2024). "Subsequently, we treated prostate cancer cells with 1 mM 8-Br-cGMP, which resulted in the phosphorylation of HSPB6 and increased expression of Cleaved-Caspase3." (PMID 38374143, 2024). "In this study, we aimed to investigate the correlation between HSPB6 expression in prostate cancer and patient prognosis." (PMID 38374143, 2024). "Our research proposes an innovative approach for prostate cancer treatment, focusing on HSPB6 as a target gene." (PMID 38374143, 2024). "Our findings revealed that HSPB6 downregulation in prostate cancer correlated with a poor prognosis." (PMID 38374143, 2024). "Subsequently, we collected tissue samples from patients and conducted validation in mRNA and protein levels, confirming that HSPB6 expression is lower in prostate cancer than in normal prostate tissue." (PMID 38374143, 2024). "To evaluate disease-free survival (DFS), we utilized data from TCGA database and conducted a DFS analysis, which revealed that prostate cancer patients with lower HSPB6 expression had poorer disease-free survival rates." (PMID 38374143, 2024). "To test this hypothesis, we constructed an HSPB6 overexpression plasmid and selected two prostate cancer cell lines, DU145 and C4-2, with the lowest HSPB6 expression for further investigation." (PMID 38374143, 2024). "Moreover, we discovered that HSPB6 can be phosphorylated and activated by 8-Br-cGMP, leading to apoptosis in prostate cancer cells by activating Cofilin." (PMID 38374143, 2024). "Additional functional experiments supported that 8-Br-cGMP could phosphorylate HSPB6 and induce apoptosis in prostate cancer cells." (PMID 38374143, 2024). "Additionally, we observed a reduction in mitochondrial membrane potential in the HSPB6 overexpression group compared to the control group, indicating that HSPB6 induced apoptosis in prostate cancer cells." (PMID 38374143, 2024). "Moreover, analysis of immunohistochemical data from the HPA database revealed HSPB6 expression in high-grade prostate cancer was lower than in low-grade prostate cancer." (PMID 38374143, 2024). "This further substantiates that prostate cancer tissues with high HSPB6 expression demonstrate elevated levels of apoptosis and reduced proliferation, yet the relationship with migration remains unclear." (PMID 38374143, 2024). "Silencing E2F1 upregulated HSPB6 expression, promoting apoptosis in prostate cancer cells." (PMID 38374143, 2024). "HSPB6 activates Cofilin and can induce apoptosis in prostate cancer cells." (PMID 38374143, 2024). "CCK8 results demonstrated that the combination of quinidine and 8-Br-cGMP in vitro more effectively inhibited the growth of prostate cancer cells, and knocking down HSPB6 could reverse this effect." (PMID 38374143, 2024).
prostate carcinoma (continued). "Interestingly, we additionally found that HSPB6 expression in castration-resistant prostate cancer (CRPCs) and neuroendocrine prostate cancer (NEPCs) was lower than in primary prostate cancer." (PMID 38374143, 2024). "The downregulation of HSPB6 expression in prostate cancer suggests it may function as a tumor suppressor gene in this context." (PMID 38374143, 2024). "Additionally, we divided prostate cancer into groups based on the Gleason score and noticed that the expression of HSPB6 progressively decreased with higher Gleason scores." (PMID 38374143, 2024). "In this study, we investigated the role of HSPB6 in prostate cancer progression." (PMID 38374143, 2024). "We hypothesized that elevated HSPB6 expression in prostate cancer could inhibit malignant tumor behavior." (PMID 38374143, 2024). "However, there is a significant gap in our understanding of the role of HSPB6 in prostate cancer." (PMID 38374143, 2024). "To understand the mechanism regulating HSPB6 expression in prostate cancer, we performed a series of bioinformatics analyses and identified E2F1 as the only factor with a clear correlation with HSPB6." (PMID 38374143, 2024). "Due to the lack of comprehensive knowledge of HSPB6 in prostate cancer, we selected it for a future study." (PMID 38374143, 2024). "Through the analysis of seven datasets (TCGA, GSE30521, GSE4602, GSE55945, GSE69223 GSE104131, and GSE200879), we identified two upregulated genes (AMACR and GCNT1) and seven downregulated genes (TGFB3, SRD5A2, PGM5, HOXD10, AOX1, HSPB6, and SNAI2) in prostate cancer compared to normal tissue." (PMID 38374143, 2024). "HSPB6 was reported to suppress the MAPK family, including JNK and the PI3K/Akt pathway, and the downregulated ACACA curbed prostate cancer growth." (PMID 35516441, 2022).
bladder cancers (1 paper, 2024). "Our study focuses on HSPB6, a small heat shock protein whose reduced expression in bladder cancer suggests a role in tumor biology." (PMID 39608715, 2024). "Rescue experiments showed that after overexpression of TCF7L1 and knocking down HSPB6, the expression of these proteins was reversed, indicating that TCF7L1 targeting HSPB6 is involved in the pathological process of EMT in bladder cancer." (PMID 39608715, 2024). "These in vivo findings collectively emphasize the strong anti-tumor properties of HSPB6 overexpression in combatting bladder carcinoma, suggesting its potential utility as a therapeutic intervention." (PMID 39608715, 2024). "In our investigation of HSPB6's influence on the growth of bladder carcinoma within a live setting, we utilized a xenograft tumor model in male BALB/c nude mice." (PMID 39608715, 2024). "Notably, stage IV bladder cancers show a higher expression of HSPB6 compared to stages II and III." (PMID 39608715, 2024). "Compared with the control group, the phosphorylation levels of PI3K, AKT, and mTOR were significantly reduced after HSPB6 overexpression, suggesting that HSPB6 inhibited the activation of PI3K/AKT/mTOR signaling pathway in bladder cancer." (PMID 39608715, 2024). "Exploring the transcriptional regulation of HSPB6, our investigation extended to the expression of TCF7L1 within bladder cancer tissues." (PMID 39608715, 2024). "From these results, it becomes evident that HSPB6 knockdown significantly counteracts the growth-inhibitory and anti-migratory effects imparted by TCF7L1 overexpression in bladder cancer cells." (PMID 39608715, 2024). "This emphasizes the crucial function of HSPB6 in facilitating the inhibitory effect of TCF7L1 on the progression of BLCA cells, shedding light on the complexities of their regulatory interaction within the cellular environment of bladder cancer." (PMID 39608715, 2024). "Therefore, HSPB6 serves a critical function not only in regulating EMT but also in suppressing the PI3K/AKT/mTOR signaling pathway, further underscores its potential as a therapeutic target in the treatment of bladder cancer." (PMID 39608715, 2024).
bladder urothelial carcinoma (1 paper, 2023). "In this study, we also found that the C11 cluster specifically expresses HSPB6, which is currently focused on bladder urothelial carcinoma (BLCA)." (PMID 37588985, 2023).
cerebral amyloid angiopathy (1 paper, 2018). "The low-activity chaperones HspB2, HspB6 and HspB8 specifically associate with fibrillar amyloid β rather than non-aggregated forms in a hereditary cerebral amyloid angiopathy caused by the rapidly aggregating amyloid β1–40 carrying the “Dutch” mutation 22Glu → Gln." (PMID 29969581, 2018).
dystrophin deficiency (1 paper, 2010). "Hspb6, which associates with actin, is a cardioprotector under stressful conditions and its mRNA was downregulated in association with dystrophin deficiency in this experiment." (PMID 20515474, 2010).